PARP1 (poly(ADP-ribose) polymerase 1)
Diseases named in the same sentence as PARP1 in open-access papers (continued):
Sharing a sentence is not in itself a finding about the gene and the disease.
ovarian carcinoma (continued). "Taken together, KAT6A LLPS was enhanced in PARPi‐resistant ovarian cancer cells, and strengthens the interaction between KAT6A and PARP1." (PMID 38973255, 2024). "Clinical trials have shown the effectiveness of PARP1 inhibitors such as olaparib 1, rucaparib 2, and niraparib 3 in improving patient survival in BRCA-mutant breast and ovarian cancers." (PMID 39456202, 2024). "Therapeutic studies with Talazoparib (BMN673, a PARP1/2 inhibitor) significantly increased the frequency of activated NK cells with the enhanced secretion of IFN-γ and TNF-α in the TME of a murine ovarian cancer model." (PMID 36829496, 2023). "HMGB3 is a novel interactor of PARP1 that can stimulate the PARylation activity of PARP1 and inhibit PARP trapping, resulting in olaparib resistance in ovarian cancer." (PMID 36909172, 2023). "RT-qPCR analysis revealed that URI1, PAK2, PARP1, CLU, and TIMP3 were significantly upregulated, while UBB, RPL11, CAV1, NUPR1, and Hsp90ab1 were significantly downregulated in the ovarian cancer samples." (PMID 37124501, 2023). "The authors showed that their treatment-induced 55% insertions or deletions (indels) in PARP-1-positive SKOV3 cells and induced SKOV3 cell apoptosis in mice with ovarian cancer." (PMID 37842166, 2023). "In a PARP-1-positive ovarian cancer model, 68Ga-DOTA-Olaparib displayed a high potential to detect PARP-1 expression quantitatively." (PMID 37145164, 2023). "The PARP1 inhibitor, rucaparib, has recently been approved by the FDA for the treatment of ovarian cancer." (PMID 37124501, 2023). "Another study showed that in ovarian cancer cells, Ets-1 activates PARP-1 expression synergistically with histone modification H3K9 by binding to the hypomethylated EBS present in the PARP1 promoter." (PMID 37686260, 2023). "Recently, newly developed inhibitors targeting PARP-1 and PARP-2 can selectively kill ovarian cancer cells and prolong the overall survival of patients with this disease 11-15." (PMID 38021157, 2023). "We also found that apoptosis-related genes, URI1, PAK2, PARP1, CLU and TIMP3, were highly expressed, while immune-related genes, UBB, RPL11, CAV1, NUPR1 and Hsp90ab1, were lowly expressed in ovarian cancer cells." (PMID 37124501, 2023). "Niraparib tosylate monohydrate is a tosylate salt form of niraparib which is a PARP-1 and PARP-2 inhibitor and has an effective and powerful antineoplastic activity against ovarian cancer." (PMID 37110218, 2023). "Over the last decade, the most successful clinical application in the field of SL is the development of poly (ADP-ribose) polymerase-1 (PARP-1) inhibitors in BRCA1/2-mutant breast and ovarian cancers." (PMID 36761420, 2022). "Olaparib is a multitarget PARP inhibitor (PARP1, PARP2, and PARP3 enzymes) with activity in ovarian cancer as well as other solid tumors." (PMID 36077726, 2022). "Here we provide strong data showing that NR1D1 is a DDR repressor in ovarian cancer cells as well, but that this regulation occurs through a direct interaction of NR1D1 with both PARP1 and BRCA1." (PMID 34743206, 2022). "CRISPR/Cas9-loaded cancer-derived EVs suppress expression of poly (ADP-ribose) polymerase-1 (PARP-1), enhance the chemical sensitivity of ovarian cancer cells to cisplatin and induce cell apoptosis." (PMID 35915054, 2022). "However, the clinical relevance of PARP1 mutations has not yet been fully clarified in a larger number of patients, and it will, therefore, be important to know the prevalence and potency to affect PARPi efficacy in ovarian cancer patients." (PMID 35626108, 2022). "Several genes have been confirmed to be closely related to the occurrence and progression of ovarian cancer, including SNAI2, VCAM1, BRCA1, MMP2, MECOM, MXS1, PARP1 and so on." (PMID 35090503, 2022). "The expression of poly (ADP-ribose) polymerase-1(PARP-1) was inhibited by the exosomes loaded with CRISPR/Cas9, which activated the apoptotic pathway and inhibited the proliferation of ovarian cancer cells." (PMID 35198064, 2022).
ovarian carcinoma (continued). "Our study improves the current understanding of PARP1 function, highlights the potential that the anti-tumor efficacy of PARP1i may not only rely on DNA damage repair mechanisms and informs on the rational design of PARP1i combination therapies in ovarian cancer." (PMID 34686201, 2021). "In this two-center case-control study, 19 potentially functional SNPs in six BER-related genes (hOGG1, APE1, PARP1, FEN1, LIG3 and XRCC1) was genotyped in 196 ovarian cancer cases and 272 cancer-free controls." (PMID 33391423, 2021). "The expression of poly ADP-ribose polymerase (PARP1), PD-L1, and CD8 in human ovarian cancer tissues was detected by immunohistochemistry(IHC)." (PMID 34620163, 2021). "PARPi is the most promising therapy for breast and ovarian cancers with HRD, and PARP-1 is a potential target." (PMID 32863940, 2020). "PARP1 and PARP2 dual inhibitors, such as olaparib, have been recently FDA approved for the treatment of advanced breast and ovarian cancers." (PMID 32221289, 2020). "Niraparib (also formerly known as MK-4827) is a novel, highly selective, and orally available PARP-1 and PARP-2 small molecule drug developed by Tesaro, approved by FDA in 2017 to treat ovarian cancer." (PMID 32509471, 2020). "Olaparib is the first inhibitor of the PARP enzymes 1, 2, and 3 (PARP-1, PARP-2, and PARP-3 respectively) developed in ovarian cancer." (PMID 31109041, 2019). "In tumors harboring defects in homologous recombination, PARP1 function is required for cellular survival, and PARP inhibitors are showing promise as effective components of breast and ovarian cancer therapies." (PMID 31636161, 2019). "Newly approved drugs targeting epidermal growth factor receptor (EGFR) and poly ADP-ribose polymerase 1 (PARP1) improved the clinical outcomes of non-small cell lung cancer and ovarian cancer patients." (PMID 28947756, 2017). "Co-treatment of VPA with DOX led to synergistic suppression of cell viability with an increase in caspase-3 activity and CDKN1A, CCNE1, PARP1, and PARP3 proteins expression in ovarian cancer cell lines." (PMID 28498322, 2017). "To validate the GSEA results, we then detected the expression of cell cycle (PCNA and PLK1), DNA replication (MCM2 and MCM3) and BER pathways-related proteins (PARP1 and PARP2) in ovarian cancer cells transiently overexpressed ARHGAP10." (PMID 27010858, 2016). "The cleaved PARP-1 protein fraction was detected in the untreated ovarian cell lysates, with the presence of the enzyme being a characteristic of tumor cells and a therapeutic target for PARP-1 inhibitors in ovarian cancer." (PMID 40219097, 2025). "Combination disrupts PARP1-Ku80 complex, enhances NHEJ over HR in G2, increases DNA double-strand breaks, cell cycle arrest, and induces persistent apoptosis, offering an effective approach for HR-proficient ovarian cancers." (PMID 39949780, 2025). "The expression level of PARP-1 in breast cancer, ovarian cancer, endometrial cancer, lung cancer, skin cancer and non-Hodgkin’s lymphoma is elevated compared to normal tissues, thus establishing a strong association between parthanatos and these cancers." (PMID 39620145, 2024). "Taken together, these results indicate that APEX1 impairs PARP1 trapping by enhancing KAT6A LLPS, and that the interaction between KAT6A and PARP1 is independent of its transcriptional regulatory function in ovarian cancer." (PMID 38973255, 2024). "Notably, the PARP1 inhibitor talazoparib (BMN 673) elicited increased numbers of peritoneal CD8+ T cells and NK cells in an ovarian cancer mouse model and increased infiltration into ex vivo spheroids, in addition to increasing IFNγ and TNFα production levels." (PMID 37752135, 2023). "For example, the PARP1 gene has been shown to be essential in tumors where BRCA1 or BRCA2 are lowly expressed, thus making PARP inhibitors a candidate for treating subtypes of breast and ovarian cancers." (PMID 36803845, 2023).
ovarian carcinoma (continued). "As for other pathways involving PARP1 and PARylation, inhibitors of PARG (enzyme that hydrolyzes PAR) have been exploited in cancer types with different sources of genomic instability, such as ovarian cancer." (PMID 36849518, 2023). "c-Jun N-terminal kinase 1/2 (JNK1/2)-mediates PARP-1 phosphorylation and subsequent degradation, while mitogen-activated protein kinase phosphatase-1 (MKP-1) inhibits the activity of JNK1/2 to suppress PARP-1 degradation in cisplatin-resistant ovarian cancer." (PMID 36694209, 2023). "Besides, the overexpression of HMGB3 significantly reduced the protein levels of cleaved caspase 3 and cleaved PARP1 following olaparib treatment, whereas ovarian cancer cells with HMGB3 knockdown showed increased levels of cleaved caspase 3 and cleaved PARP1." (PMID 35332131, 2022). "Surprisingly, we showed that even in the presence of a PARPi, NR1D1 overexpression was able to significantly inhibit HR, suggesting that the regulation of DNA repair by NR1D1 in ovarian cancer is not solely dependent on PARP1." (PMID 34743206, 2022). "Interestingly, inhibition of AKT appeared to reduce PARP1 protein level and PAR level in both PDX tumor tissue and ovarian cancer cell lines (OVCAR8 and OVCA433), although detailed mechanism is unclear." (PMID 35419627, 2022). "In conclusion, HMGB3 promoted PARPi resistance via interacting with PARP1, and the targeted inhibition of HMGB3 might overcome PARPi resistance in ovarian cancer therapy." (PMID 35332131, 2022). "Inhibition of PARP1, an enzyme that can catalyze Poly(ADP-ribose) (PAR) formation, and plays a role in DNA damage repair, was recently shown to promote ferroptosis via repressing SLC7A11 and has a synergetic effect in BRCA-proficient ovarian cancer." (PMID 34445601, 2021). "In conclusion, we have confirmed that PARP1 is essential for HR in ovarian cancer cell lines lacking BRCA2 and treatment with rucaparib, a PARP inhibitor, increases the formation of γ-H2AX foci." (PMID 34572083, 2021). "In contrast, growth arrest-specific 5 (GAS5) is an lncRNA that exerts a tumor-suppressive function in ovarian cancer through sponging miRNAs such as miR-21, and by facilitating the E2F4-mediated transcriptional repression of poly (ADP-ribose) polymerase 1 (PARP1)." (PMID 34681900, 2021). "Recent reports showed that ovarian cancer cells that acquired CR expressed high levels of mitogen-activated protein kinase phosphatase-1 (MKP-1) and PARP-1 proteins; hence, silencing MKP-1 or PARP-1 increases cisplatin sensitivity in resistant cells." (PMID 34298999, 2021). "We performed an in vivo study to increase clinical significance and successfully demonstrated that PARP1 inhibitor rucaparib, the FDA-approved chemotherapeutic drug for ovarian cancer, significantly decreased the degree of fibrosis in patient-derived keloid xenograft model." (PMID 31119062, 2019). "There are some limitations of our study, first of all, whether rapamycin can affect the apoptosis of ovarian cancer cells by targeting GAS5 expression and how to participate in GAS5 target gene (E2F4 or PARP1) regulation need to be further studied." (PMID 31391118, 2019). "The PARP1 inhibitor, rucaparib is a recently FDA-approved therapy for ovarian cancer." (PMID 31119062, 2019). "The PARP1 inhibitor, rucaparib, is a recently FDA-approved therapeutic agent for ovarian cancer." (PMID 31119062, 2019). "We hypothesized that BAP1-mutant mesothelioma might be addicted to PARP1-mediated DNA repair pathways, similar to the BRCA1/2-mutant breast and ovarian cancers." (PMID 28756516, 2017). "We hypothesized that BAP1-mutant MPM would require PARP1 for survival, similar to the BRCA1/2 mutant breast and ovarian cancers." (PMID 28756516, 2017). "As PARP1 inhibitors are currently under study in the context of phase II and phase III clinical trials, mostly for advanced or relapsed breast and ovarian cancer, the need to further understand the role of PARP1 in hematological malignancies is mandatory." (PMID 25161998, 2014).
ovarian carcinoma (continued). "Our results indicate that the biological effects of ETS in ovarian cancer might be mediated by the hypomethylated ETS motif, which induces the high expression of PARP1." (PMID 23442605, 2013). "However, in the studies conducted on ovarian cancer cell lines, it was shown that visfatin did not exert an impact on PARP1 expression." (PMID 40076482, 2025). "This has made PARP‐1 a target of interest in cancer therapeutics, and the discovery of small molecule inhibitors of PARP‐1 has recently resulted in the approval of ‘parib’ drugs such as olaparib, rucaparib, veliparib, and talazoparib for different stages of breast and ovarian cancers." (PMID 41230800, 2025). "Given that KAT6A LLPS reduces its capacity to bind chromatin, and deletion of the IDR domain from KAT6A disrupts the interaction between KAT6A and PARP1 in PARPi‐resistant ovarian cancer cells, our next inquiry focused on whether KAT6A impedes PARP1 trapping via LLPS." (PMID 38973255, 2024). "In addition to PARP1, other members of the PARP family play distinct roles in ovarian cancers." (PMID 39272943, 2024). "When PARP1-mediated ADPRylation of DDX21 is inhibited by niraparib, DDX21 is mislocalized to the nucleoplasm resulting in decreased rDNA transcription, which leads to a reduction in ribosome biogenesis, protein translation, and ultimately endometrial and ovarian cancer cell growth." (PMID 38767454, 2024). "Notably, we observed that H3K9ac deletion and/or ETS1 enrichment were effective ways to induce a decrease of PARP1 levels in SKOV3 cells and primary non-mutated and BRCA1-mutated ovarian cancer cells (Fig. 3Ei-Eiv)." (PMID 24448423, 2014). "In addition, we noted a significant negative correlation between PARP1 mRNA levels and the total number of methylated sites in both ovarian cancer and normal tissues." (PMID 23442605, 2013). "However, XRCC1 downregulation has no impact on survival of BRCA2-mutant PEO1 ovarian cancer cells, whereas PARP1 downregulation is cytotoxic." (PMID 24062981, 2013). "However, the expression and relationship between PD-L1 and CD8 on ovarian cancer is still lacking in sample studies and the correlation of PARP1, PD-L1 and CD8 remains unclear." (PMID 34620163, 2021). "PARP1 can enhance DNA methyltransferase 1 (DNMT1) expression by maintaining the unmethylated state of the DNMT1 promoter, so it can be predicted that up-regulation expression of DNMT1 may be beneficial in resisting genome-wide demethylation during the progression of ovarian cancer." (PMID 23442605, 2013).
prostate carcinoma (133 papers, 2011 to 2026). A carcinoma that arises from epithelial cells of the prostate gland. "To test this, we extracted gene expression levels for 65 proteins that were proximal to PARP1 and present at stressed replication forks, from breast, ovarian, and prostate cancer samples with wild-type or mutated BRCA1 or BRCA2 from the cBioPortal." (PMID 36350633, 2022). "Genes associated with ETV4-fusion-positive prostate cancers were used as the input, and four therapeutic candidate targets, PARP1, NQO1, HSPA5, and TOP1, and the respective selective drugs, olaparib, amrubicin, fluorouracil, and irinotecan, were identified." (PMID 36289913, 2022). "Previously, we reported that PTEN contributes to HR in prostate cancer and proposed the treatment of agents targeted against defects in HR such as PARP1 inhibitors to PTEN-deficient tumors." (PMID 33003585, 2020). "This is in close agreement with several other reports conducted globally, where homozygous mutant variant of PARP1 polymorphism rs1136410 was found linked with prostate cancer, thyroid carcinoma and systemic lupus erythematosus." (PMID 31609976, 2019). "The inhibition of PARP-1 is being exploited for the treatment of various cancers, which include DNA repair-deficient ovarian, breast, and prostate cancers." (PMID 31877876, 2019). "Since the data presented herein demonstrate that HR gene expression is controlled by PARP‐1, and that PARP‐1 enzymatic activity is increased during prostate cancer progression, there is an association between PARP‐1 activity and HR gene expression." (PMID 30467127, 2018). "High expression of TMPRSS2:Erg in prostate cancers or EWS-Fli1 in Ewing sarcoma causes DNA damages that are potentiated by PARP-1 inhibition and are followed by strong inhibition of cancer progression." (PMID 23405229, 2013). "The PARP-1 Val762Ala polymorphism has been associated with increased risk of developing cancers of the prostate, esophagus and lung." (PMID 22624032, 2012). "Small-molecule inhibition of Poly (ADP-ribose) polymerase 1 and 2 (PARP1/2) is an approved therapeutic strategy for the treatment of metastatic breast, ovarian, pancreatic and prostate cancers associated with Homologous Recombination (HR) defects, including mutations in BRCA1 gene." (PMID 40527886, 2025). "Importantly, our data show that depletion of PSIP1 results in higher sensitivity of prostate cancer cells to clastogens that cause transcription-coupled DNA damage and a PARP1 inhibitor." (PMID 38191578, 2024). "Moreover, PARP1 has been extensively implicated in regulating prostate cancer progression and development, with concomitant presence of prostatitis presenting as a high-risk factor for prostate cancer." (PMID 40032778, 2025). "The tumor-selective cytotoxic effect of combined PARP1 inhibition and irradiation was corroborated in human-derived prostate cancer organoids." (PMID 41837288, 2026). "Saruparib is a first-in-class PARP1 inhibitor with exquisite PARP1 selectivity that is being tested in the phase 1/2a PETRA trial in pretreated solid tumors, including prostate cancer, with a BRCA, RAD51, or ATM mutation." (PMID 39882554, 2025). "Currently, PARP1 inhibitors are used clinically for the treatment of BRCA-mutated breast, ovarian, pancreatic, and prostate cancers." (PMID 39982959, 2025). "These discoveries provide guidance for precision radiotherapy in prostate cancer: PARP1-EJ repair switching can serve as a criterion for patient selection, while effectively inducing tumor cell senescence is a key mechanism for successful treatment." (PMID 41367875, 2025). "These prostate cancer cells showed significantly higher sensitivity to the PARP1 inhibitor (PARPi) olaparib compared to RWPE-1 cells." (PMID 38191578, 2024). "Expression of PARP-1 cleavage in human PC-3 prostate cancer cells was used as a surrogate marker of apoptotic cell death 48 h after radiation exposure of different qualities alone or in combination with DDR inhibitors." (PMID 38672592, 2024).